APOC1 (apolipoprotein C1)
Diseases named in the same sentence as APOC1 in open-access papers (continued):
Sharing a sentence is not in itself a finding about the gene and the disease.
amyloid (2 papers, 2016 to 2025). "In addition to neurogenesis, cell adhesion/inflammation, and synaptic signaling, cholesterol metabolism, and especially lipoproteins (APOA1, APOC1, APOC3, APOF), were associated with depressive symptoms when amyloid pathology was present." (PMID 41451799, 2025). "Based on the fact that affected patients with amyloidosis also displayed hypotriglyceridemia and increased plasma levels of HDL-C as compared with non-carriers in the family, we next screened several candidate genes including the APOC3, APOC1, APOC2, APOC4, APOA4, APOA5 and APOE genes." (PMID 26790392, 2016).
central obesity (2 papers, 2011 to 2018). "Although associations between APOC1 with atherogenic dyslipidemia and vascular inflammation have been reported and replicated in the GWA study literature, we consider it a novel locus due to the strong and previously unreported associations with elevated plasma glucose and central obesity." (PMID 22022282, 2011).
esophageal cancer (2 papers, 2023 to 2025). A primary or metastatic malignant neoplasm involving the esophagus. "Then, the diagnostic and prognostic value of APOC1 in esophageal cancer was evaluated, and finally, the relationship between APOC1 and tumor immune infiltrating cells was analyzed." (PMID 36969562, 2023). "In conclusion, APOC1 may be used as a diagnostic biomarker for esophageal cancer." (PMID 36969562, 2023). "The expression of APOC1 facilitates the proliferation, migration, and invasion of esophageal cancer cells and correlates with the characteristics of the immune microenvironment." (PMID 41438761, 2025). "Apolipoprotein C1 (APOC1) is involved in tumorigenesis as an inflammation-related molecule, and its role in esophageal cancer is still unknown." (PMID 36969562, 2023).
fibrosis (2 papers, 2023 to 2024). the formation of excess fibrous connective tissue in an organ or tissue in a reparative or reactive process. "Mechanistic studies revealed that the knockdown of APOC1 could improve IgAN renal fibrosis by inhibiting the NF pathway, which may be a potential therapeutic target for improving renal fibrosis in IgAN." (PMID 37305534, 2023).
glaucoma (2 papers, 2016 to 2021). Increased pressure in the eyeball due to obstruction of the outflow of aqueous humor. "GO analysis revealed a large impact of glaucoma on positive regulation of cholesterol esterification as evidenced by the upregulation of angiotensinogen (AGT), apolipoprotein C-I (APOC1), and apolipoprotein A-IV (APOA4)." (PMID 27788204, 2016).
hippocampal atrophy (2 papers, 2019 to 2025). "Although our findings underscore APOC1’s association with neurodegeneration, further studies are necessary to elucidate the mechanisms by which APOC1 affects cortical and hippocampal atrophy, thus guiding its clinical interpretation." (PMID 40369256, 2025). "We found a potential mediating role of left hippocampal atrophy in linking the APOC1 expression and cognitive function." (PMID 40369256, 2025). "We speculate that APOC1 may contribute to cortical thinning and hippocampal atrophy through molecular mechanisms that differ from those of APOE." (PMID 40369256, 2025). "Our findings provide evidence that TOMM40 and APOC1 as candidate genes may promote the application of hippocampal atrophy rate as an early biomarker for predicting cognitive progression and detecting disease trajectories." (PMID 31760383, 2019).
Hyperglycemia (2 papers, 2023 to 2024). An increased concentration of glucose in the blood. "ApoC1 has lost its ability to inhibit CETP in patients with T1D, and in vitro glycation of apoC1 increases CETP activity, suggesting that hyperglycemia could be a factor implicated in the loss of the inhibitory effect of apoC1 on CETP." (PMID 39330494, 2024). "Thus, we hypothesized that hyperglycemia could be a factor implicated in the loss of the inhibitory effect of apoC1 on CETP observed in people with T1D." (PMID 39330494, 2024). "Glycation, a consequence of hyperglycemia, is suspected to be involved in the apoC1 inability to inhibit CETP." (PMID 39330494, 2024). "Data from our study indicate that hyperglycemia does not seem to be a major factor implicated in the loss in the ability of apoC1 to inhibit CETP activity observed in T1D." (PMID 39330494, 2024). "Hyperglycemia in vivo does not seem to be a major factor implicated in the loss of apoC1 ability to inhibit CETP activity observed in T1D." (PMID 39330494, 2024). "This reinforces the fact that improving hyperglycemia does not restore apoC1 function." (PMID 39330494, 2024). "Moreover, the lack of difference in apoC1 isoforms in mass spectrometry between uncontrolled T1D patients at baseline and improved glycemic control at 3 months reinforces the idea that hyperglycemia, via glycation, does not play a major role in vivo in the loss of function observed in T1D." (PMID 39330494, 2024).
lymphoma (2 papers, 2022 to 2025). A malignant (clonal) proliferation of B- lymphocytes or T- lymphocytes which involves the lymph nodes, bone marrow and/or extranodal sites. "Next, we assessed APOC1 expression in lymphoma tissues from 46 DLBCL patients using RT-qPCR and Western blot, with lymph node tissues from 13 RHL patients (a benign tumor) serving as negative controls." (PMID 39873475, 2025). "ACTB, aaaaaaaa2M, APOH, TIMP-1, CD44 antigen, Ig heavy chain V region GOM, and APOC1 are novel candidate proteins and might serve as a lymphoma biomarker in dogs." (PMID 35765478, 2022). "The first reported serum proteins in canine lymphoma were ACTB, Ig heavy chain V region GOM, TIMP-1, APOH, CD44, APOC1, and β2M." (PMID 35765478, 2022). "Potential novel candidate biomarkers in canine lymphoma were ACTB, β2M, TIMP-1, CD44 antigen, Ig heavy chain V region GOM, APOC1, and APOH." (PMID 35765478, 2022).
melanoma (2 papers, 2021 to 2024). A malignant, usually aggressive tumor composed of atypical, neoplastic melanocytes. "According to the analysis of human melanoma scRNA-seq, myeloid cells associated with responders showed a relatively high expression of PLTP, APOC1, APOE, MT1G, and MT1H." (PMID 34966676, 2021).
metastatic tumor (2 papers, 2021 to 2023). "We also found that the expression of APOC1 gradually increased from normal tissues to CRC primary tumor tissues and to CRC liver metastatic tumor tissues." (PMID 34081622, 2021).
nephrotic syndrome (2 papers, 2017 to 2023). A collection of symptoms that include severe edema, proteinuria, and hypoalbuminemia; it is indicative of renal dysfunction. "Group 1 was characterized by major risk genes for developing LOAD (APOC1 and APOC1P1) and immune-related genes (RELB and CBLC), whereas group 2 was characterized by genes associated with kidney disorders, such as nephrotic syndrome (AXDND1, FBP1, and MIR2278)." (PMID 37386009, 2023).
pneumonia (2 papers, 2019 to 2022). An acute, acute and chronic, or chronic inflammation focally or diffusely affecting the lung parenchyma, caused by an infection in one or both of the lungs (by bacteria, viruses, fungi, or mycoplasma.). "ApoC1 has been shown to provide protection against Klebsiella pneumoniae-induced pneumonia by increasing the early immune response and preventing lethality in mice." (PMID 36459524, 2022). "ApoC1 was also the marker with the best sensitivity and specificity for detecting pneumonia in children." (PMID 31779116, 2019).
psoriasis (2 papers, 2024 to 2025). An autoimmune condition characterized by red, well-delineated plaques with silvery scales that are usually on the extensor surfaces and scalp. "The aim of this study was to evaluate the potential associations between serum concentrations of apolipoproteins (ApoA1, ApoA2, ApoB, ApoC1, ApoC3, ApoD, ApoE, ApoH, and ApoJ) and various clinical and biochemical markers in patients with psoriasis." (PMID 40137160, 2025). "Our findings, which show higher serum ApoC1 levels in patients with more severe psoriasis, align with the broader evidence linking apolipoproteins to cardiovascular risk." (PMID 40137160, 2025). "While limited prior research has primarily focused on apolipoproteins such as ApoA1, ApoA2, ApoB, ApoC1, ApoC3, and ApoE in psoriasis, our study uniquely extends this scope by also evaluating ApoD, ApoH, and ApoJ in this patient population for the first time." (PMID 40137160, 2025). "While ApoA1 and ApoB in psoriasis have been the primary focus of research due to their established roles in lipid metabolism and cardiovascular risk, other apolipoproteins, such as ApoA2, ApoC1, ApoC3, ApoD, ApoE, ApoH, and ApoJ, have not been widely studied in psoriasis." (PMID 40137160, 2025).
renal fibrosis (2 papers, 2023). A final common manifestation of a wide variety of chronic kidney diseases characterized by glomerulosclerosis and tubulointerstitial fibrosis. "Apolipoprotein C1 is thought to be a central secretory gene associated with IgAN, and mechanistic studies have indicated that knockdown of apolipoprotein C1 can ameliorate IgAN and renal fibrosis by inhibiting the NF-ƙB pathway." (PMID 38293668, 2023). "APOC1 exacerbated renal fibrosis, possibly in part by activating the NF-κB pathway in IgAN." (PMID 37305534, 2023). "There may be some correlation between APOC1 expression and renal fibrosis." (PMID 37305534, 2023).
schizophrenia (2 papers, 2021 to 2022). A major psychotic disorder characterized by abnormalities in the perception or expression of reality. "A meta-analysis between schizophrenia patients and healthy controls was performed, with the results suggesting four apolipoproteins, APOA1, APOA2, APOC1 and APOC3 (downregulated), and ficolin-3 (upregulated) as potential biomarkers of the disorder." (PMID 35563307, 2022). "The statistical analyses showed that MDD patients could be distinguished from schizophrenia patients and healthy controls by the lack of apolipoprotein C1 (Apo C1), which, in fact, was detected in healthy controls and schizophrenia patients." (PMID 34361610, 2021).
steatosis (2 papers, 2022 to 2023). Increased lipid within the cytoplasm of cells. "The heatmap showed that the B4 cluster expressed a series of lipid-metabolism-associated genes, such as APOA1, APOA2, and APOA3, and UMAP plotting also showed that B4 cells highly expressed APOC1 and APOE, implying that the B4 cluster may be associated with steatosis in the ALC group." (PMID 36817578, 2023).
thyroid cancer (2 papers, 2022 to 2023). "First, we verified the expression of 9 immune-related prognostic factors, AKAP12, APOC1, TIMP3, ADAMTS9, ANK2, HTRA3, SYNDIG1, ​​ADAMTS5 and DACT1, in 11 thyroid cancer cell lines in the CCLE database." (PMID 36591507, 2022).
viral infection (2 papers, 2020). "Expression of these genes is associated with movement (MMP9, SPP1, ALCAM, and others), viral infection (APOC1, LGALS3, CD63, and others), and recruitment of phagocytes (APOE, CHI3L1, LGALS3, and others)." (PMID 32723919, 2020). "Apolipoprotein C1 in hepatitis C virus is related to morphogenesis and virus infection." (PMID 32942608, 2020).
Adrenocortical carcinoma (1 paper, 2023). "However, the expression level of APOC1 in tumors was significantly lower than in normal tissues in Adrenocortical carcinoma (ACC)." (PMID 36969562, 2023).
anaplastic oligodendroglioma (1 paper, 2022). A WHO grade III oligodendroglioma with focal or diffuse malignant morphologic features (prominent nuclear pleomorphism, mitoses, and increased cellularity). "As shown in the single patients with anaplastic oligodendroglioma, pilocytic astrocytoma, and the (WHO unclassified) spindle cell tumor, the postoperative direction (rise/fall) and the amount of ApoC1 serum level variation were subject to an individual course." (PMID 36101402, 2022).
aneurysm (1 paper, 2009). Bulging or ballooning in an area of an artery secondary to arterial wall weakening. "We observed downregulation of the genes encoding kininogen (kng1), Apolipoprotein CI (Apoc1) and the neutrophil-associated leucine-rich alpha-2-glycoprotein 1 (Lrg1) amongst others, in aortas of mice resistant to aneurysm suggesting that they may be pathological genes." (PMID 19580648, 2009).
astrocytoma (1 paper, 2022). "Previous work using a human astrocytoma cell line identified a PPAR response element (PPRE) in a similar region (downstream of APOE and upstream of APOC1) that was important in driving macrophage expression of APOE." (PMID 34878094, 2022).
Atrophy (1 paper, 2025). Any weakening or degeneration, especially through lack of use. "In this study, we systematically examined the association between APOC1 expression and CTh atrophy and their combined effects on the conversion from MCI to AD." (PMID 40369256, 2025). "Elevated APOC1 levels were particularly notable in the regions affected by CTh atrophy." (PMID 40369256, 2025).
B-cell lymphoma (1 paper, 2022). "In T-cell lymphoma, serum apolipoprotein C1 (APOC1, p=0.05) was elevated compared to B-cell lymphoma and healthy dogs." (PMID 35765478, 2022).
bone metastasis (1 paper, 2024). Transfer of a neoplasm from its primary site to bones. "Next, we analysed immune cell infiltration in patients with PCa and with or without bone metastasis, finding a positive correlation between CFH, APOC1 and LGALS1 and various immune cell types." (PMID 39098992, 2024).
Brain atrophy (1 paper, 2025). Partial or complete wasting (loss) of brain tissue that was once present. "Multiple lines of evidence have linked APOC1 to brain atrophy and neurodegenerative changes in AD." (PMID 40369256, 2025). "Moreover, APOC1 polymorphism influences HV, which may have a significant effect on brain atrophy compared to that of APOE." (PMID 40369256, 2025). "However, the relationship between APOC1 expression and brain atrophy lacks evidence and requires further investigation." (PMID 40369256, 2025).
brain tumors (1 paper, 2022). "The present study examined 230 ApoC1 serum values in a group of 96 neurosurgical patients, comparing a control set of 11 patients with spinal interventions to 85 patients with brain tumors." (PMID 36101402, 2022). "ApoC1 serum levels in neurosurgical patients have not been reported in the literature, though theoretically, ApoC1 from brain tumors can leak through the damaged blood–brain barrier into the bloodstream." (PMID 36101402, 2022).
cervical tumour (1 paper, 2021). "For example, the relative expression of APOC1 in cervical tumour tissues was obviously higher than that in adjacent nontumour tissues (P < 0.05)." (PMID 34857818, 2021).
Cholecystitis (1 paper, 2020). The presence of inflammatory changes in the gallbladder. "The upregulation of APOC1 might reflect the existence of bacterial infection in AA than the diseases in the CON group, such as cholecystitis and pancreatitis." (PMID 32337245, 2020).
chronic lymphocytic leukemia (1 paper, 2019). "Some of the genes detected in our study include the apolipoprotein gene cluster (APOC1, APOC2, APOE), which are shown to have tight linkage with a chronic lymphocytic leukemia-associated translocation breakpoint." (PMID 31013791, 2019).
Coats disease (1 paper, 2016). Coats disease (CD) is an idiopathic disorder characterized by retinal telangiectasia with deposition of intraretinal or subretinal exudates, potentially leading to retinal detachment and unilateral blindness. "Interestingly, several genes, including APOC1 and FGB, were up-regulated in the AH samples of the patients with Coats' disease." (PMID 27416065, 2016).
cortical atrophy (1 paper, 2025). "Our results reinforce these prior observations by demonstrating a significant role of APOC1 in accelerating cortical atrophy during the conversion from MCI to AD." (PMID 40369256, 2025). "Additionally, APOC1 has been shown to exacerbate soluble Aβ oligomer-induced neuronal cell death in vitro, which may help explain the pronounced hippocampal and cortical atrophy observed in cognitively impaired patients." (PMID 40369256, 2025).
dyslipidaemia (1 paper, 2024). "This may hinder the control exercised by this unique lncRNA on adipocyte APOC1, thus compromising adipose tissue function and lipid homeostasis to the point of affecting dyslipidaemia." (PMID 39362599, 2024).
endometrial cancer (1 paper, 2024). Primary or metastatic malignant neoplasm involving the endometrium (mucous membrane that lines the endometrial cavity). "Two biomarkers (APOA1 and its modified form) were downregulated, while two (APOC1 and its modified form) were upregulated in endometrial cancer patients; these differences were also significant for stage I patients." (PMID 39194522, 2024). "Several blood-based protein biomarker candidates for endometrial cancer detection were suggested, including the Apolipoprotein family (APOA1/4, APOC1/2/3, and APOE), Clusterin (CLU), Inter-alpha-trypsin inhibitor heavy chain (ITIH2 and ITIH4), and Antithrombin III (ATR/SERPINC1)." (PMID 39194522, 2024).
endothelial dysfunction (1 paper, 2025). In vascular diseases, endothelial dysfunction is a systemic pathological state of the endothelium (the inner lining of blood vessels) and can be broadly defined as an imbalance between vasodilating and vasoconstricting substances produced by (or acting on) the endothelium. "Upregulated proteins (e.g., CRP, C9, APOC1) correlated with visceral adiposity, systemic inflammation, and endothelial dysfunction." (PMID 40981199, 2025).
endotoxemia (1 paper, 2022). "Contrary to this, in other studies, the measured plasma levels of ApoC1 were positively correlated with the proinflammatory response of patients undergoing extracorporeal circulation and who presented endotoxemia during reperfusion." (PMID 36459524, 2022).
heart failure (1 paper, 2022). Inability of the heart to pump blood at an adequate rate to meet tissue metabolic requirements. "A second group set up a prospective study in patients with heart failure and measured plasma apoC1 using LC-MRM-MS at inclusion before a 3 year follow-up." (PMID 36471375, 2022).
Huntington disease (1 paper, 2024). Huntington disease (HD) is a rare neurodegenerative disorder of the central nervous system characterized by unwanted choreatic movements, behavioral and psychiatric disturbances and dementia. "Parkinson's and Huntington's disease were both enriched by APOC1, NUSAP1, NR4A2, ADRB2 and ZNF331." (PMID 39098992, 2024).
keloid (1 paper, 2022). An irregularly shaped, elevated mark on the skin caused by deposits of excessive amounts of collagen during wound healing. "Furthermore, two modules of macrophages (Module2: highly expresses RNASE1, C1QA, CD163, CD14, C1QC, FCGRT, and MS4A7; Module10: highly expresses APOC1, CTSB, CTSL, and TYROBP), which exhibited the characteristics of TAMs, increased significantly in keloid." (PMID 35990663, 2022).
leukaemia (1 paper, 2020). "In our study, we identified an LTR2 element, the genetic and epigenetic perturbation of which suppressed cell growth and induced apoptosis of leukaemia cell lines by altering lipid-related APOC1 expression." (PMID 32665538, 2020). "Strikingly, we find that either genetic or epigenetic perturbation of a single ERV-derived enhancer element leads to impaired cell growth by modulating expression of the APOC1 gene, suggesting that the activation of this particular ERV has a driving role in leukaemia cell phenotype." (PMID 32665538, 2020).
Lipid metabolism disorders (1 paper, 2023). "Lipid metabolism disorders and immunoinflammatory responses are critical in the development and progression of DN patients, which means that APOC1 may be also involved in the development of DN." (PMID 36891052, 2023).
lung adenocarcinoma (1 paper, 2023). A carcinoma that arises from the lung and is characterized by the presence of malignant glandular epithelial cells. "APOC1 expression was not significantly different between Lung adenocarcinoma (LUAD) and normal tissues." (PMID 36969562, 2023).